E2F1 (E2F transcription factor 1)
Diseases named in the same sentence as E2F1 in open-access papers (continued):
Sharing a sentence is not in itself a finding about the gene and the disease.
cancer (continued). "Of note, the CDK4/6 inhibitor palbociclib, which is clinically used in adjuvant cancer therapy, reduced the expression of E2F1, MYBL2, and FOXM1 and of endoreduplications." (PMID 40319068, 2025). "E2F1 hyperactivation in cancer supports the increased demand for protein synthesis in rapidly dividing cells." (PMID 40517236, 2025). "Our result shows that reducing c-Myc and E2F1, which are vital in m6A-regulated cancer progression, is crucial in the combination therapy of FB23 and ibrutinib." (PMID 41281757, 2025). "Enhanced E2F activity has been utilized to drive gene expression preferentially in cancer cells using E2F target promoters, such as the E2F1 promoter." (PMID 41439972, 2025). "Our results showed that both cell lines are sensitive to palbociclib, reinforcing the fact that CDK inhibition is effective in treating cancers with the canonical Rb-E2F1 pathway." (PMID 40519166, 2025). "Another well-known transcription factor that has been identified in recent years as a major mediator of cancer cell aggressiveness is E2F1." (PMID 40299510, 2025). "SIRT1 (discussed in “E2F1-dependent apoptosis in cancer therapy”) has been demonstrated to promote cancer chemoresistance." (PMID 40517236, 2025). "The involvement of the AHR and its associated genes in CRC was confirmed, demonstrating its likely role through E2F1 in this cancer." (PMID 41465541, 2025). "They found that EZH2 and E2F1 work together to regulate the cell cycle and prevent cell death, which helps cancer cells grow." (PMID 41413688, 2025). "Here we show artificial promoters, in which E2F-responsive elements of the TAp73 gene are tandemly connected to the ARF core promoter, exhibited higher cancer cell specificity than E2F1, hTERT, or ARF promoters." (PMID 41439972, 2025). "Further western blotting analysis manifested that E2F1 deficiency reduced the expression of OCT4 and CD44, which are key regulators of cancer stemness, in Huh-7 and Hep3B cells." (PMID 40221814, 2025). "We also analyzed the differential expression of Sox4, E2f1, Trpv4 and Trim6, which are the genes important for cancer stem cell behavior and function." (PMID 40568073, 2025). "This scenario would suggest the existence of a feedback loop between E2F1 and TAp73 in cancer cells, that would be short‐circuited by BMT9 treatment." (PMID 39090849, 2025). "The identification of CCNA2, CHK1, CHK2, E2F1, and TOP2A as core genes in HCC is consistent with previous research that has linked these genes to cancer progression." (PMID 40573296, 2025). "Accordingly, we focused on E2F1, which binds directly to MUC1-C, is overexpressed in cancer, drives cell proliferation and has been linked to promoting EBV latency." (PMID 40764753, 2025). "The expression of E2F1 in the pan-cancer analysis indicated that it had a higher expression in tumors than in normal tissue." (PMID 41050059, 2025). "Lending support to our study, prior research has shown that the m6A modifications of Pbx1 and E2F1 affected their stability in cancer cells." (PMID 39559922, 2025). "E2F1 and hTERT promoters have been utilized to regulate gene expression in a cancer cell-specific manner." (PMID 41439972, 2025). "Stabilization of E2F1 was revealed as another molecular mechanism for cancer promotion by the SET–PP2A axis." (PMID 38141761, 2024). "We elaborate on distinct mechanistic networks involved in cancer progression, emphasizing the potential of the lncRNAs/E2F1 axes as promising targets for cancer therapy." (PMID 39119602, 2024).
cancer (continued). "Accumulating evidence revealed that the degradations of c-Myc and E2F1 through PP2A inactivation are the dominant mechanisms of SET-mediated cancer cell stemness." (PMID 38141761, 2024). "Existing evidence has indicated that E2F1 was an essential predictor of prognosis in cancer patients." (PMID 39119602, 2024). "E2F1 impacts malignant behaviors in various types of human cancers, thus it serves as a candidate for anti-cancer treatment." (PMID 39119602, 2024). "To confirm the direct impact of METi-dependent E2F1 depletion on purine synthesis, we transiently expressed E2F1 in MET-driven GTL-16 cancer cells." (PMID 38957115, 2024). "Taken together, miR-34a is an important regulator of leukemogenesis through different mechanisms including inhibition of CDK4, MYB, and SIRT1 expression, and/or suppression of B-Myb and E2F1 expression, leading to cell cycle arrest in cancer cells." (PMID 38361758, 2024). "E2F1 significantly contributes to cell cycle regulation and apoptosis induction in human cancer cells." (PMID 39119602, 2024). "Although previous sections have touched upon the involvement of lncRNAs in cancer progression, we will delve into current investigations demonstrating the molecular actions of these lncRNAs regulated by specifically TF, namely, E2F1 in different cancers." (PMID 39119602, 2024). "Throughout this review, we have emphasized the critical role of lncRNAs and E2F1 in oncogenesis and the progression of various cancer types by regulating diverse cellular processes and signaling networks." (PMID 39119602, 2024). "Research shows that the transcription factor E2F1 plays a critical role in modulating malignant progression and chemoresistance in cancer." (PMID 39242557, 2024). "Since E2F1 orchestrates the immunomodulatory network via IL-6, we first investigated the effect of IL-6 on the cancer-immune crosstalk." (PMID 39544930, 2024). "E2F1 is deregulated in the setting of human cancers including breast, colorectal, lung, prostate, ovarian, and bladder cancer." (PMID 39119602, 2024). "The core gene E2F1 regulates metabolism in cancer cells by enhancing glycolysis and has been shown to regulate oxidative metabolic genes in muscle and fat." (PMID 38486026, 2024). "H19 promotes cancer progression through the H19/miR-675/E2F transcription factor 1 (E2F-1) signaling pathway." (PMID 38559560, 2024). "By influencing cellular processes like cell proliferation and metastasis in cancer, lncRNAs become integral components of the E2F1 regulatory networks." (PMID 39119602, 2024). "This review aims to elucidate the intricate gene regulatory programs between lncRNAs and E2F1 in cancer progression." (PMID 39119602, 2024). "E2F1 is found to play a role in a variety of cancer types, including breast, gastric, and colorectal cancer, and has been shown to promote cell proliferation and inhibit apoptosis." (PMID 38360622, 2024). "Our results point to the crucial roles of GTF2H2 in the activation of tumor suppressor genes by deregulated E2F1, thereby providing a potential new target in cancer treatment." (PMID 39595534, 2024). "E2F1 is highly upregulated in late-stage tumors and promotes cancer invasion and metastasis in prostate cancer and colon cancer." (PMID 38157850, 2024). "Evidence continually emerges supporting the link between lncRNAs and E2F1 in regulating tumorigenesis in different cancers." (PMID 39119602, 2024). "Especially interesting finding was that the DUSP6 knockdown cells displayed a gene expression pattern linked to dormant cancer cells such as inhibition of MYC, E2F1 targets, and the PI3K/AKT/mTOR signaling, as well as activation of the interferon response." (PMID 38886591, 2024).
cancer (continued). "The search for triggers and clinically useful markers of metastasis revealed that E2F1 critically orchestrates epigenetic cancer evolution and therapy resistance." (PMID 39544930, 2024). "Concurrently, SNHG15 sponged miR-24-3p to upregulate the mRNA expression of E2F1, which suppressed ferroptosis and promoted cancer progression." (PMID 39119602, 2024). "The overexpression of E2F1 is a sign of transformation and progression in various types of cancer, such as melanoma, bladder cancer, and breast and lung carcinomas." (PMID 38157850, 2024). "Other transcriptional factors, such as E2F1, are expressed by a variety of solid tumors and are involved in the regulation of cancer cells’ proliferation and self-renewal." (PMID 38794128, 2024). "E2F1 has been found to promote the proliferation of cancer cells by transactivating cell cycle-related kinases." (PMID 36977989, 2023). "Mechanistically, the E2F1/Rb pathway is likely critical for the regulation of cell growth and the development of cancer." (PMID 38062013, 2023). "The TF E2F1 has many roles in the regulation of diverse oncogenic-related cellular pathways and phenotypes in several types of cancers." (PMID 37690684, 2023). "E2F1 and E2F4 chromatin immunoprecipitation sequencing (ChIP-seq) data analyses from cancer cells (E2F1 ChIP-seq, E2F4 ChIP-seq, RBL2/p13055) further indicated the binding of E2F1 and E2F4 in the proximity of WNT4 and WNT8A." (PMID 37725511, 2023). "High E2F1 expression was significantly correlated with individual cancer stages in BC from UALCAN and GEPIA databases." (PMID 37160894, 2023). "Further, PRMT5/E2F1 expression and cortactin/CTTN expression showed positive correlations across different types of cancer in the Cancer Genome Atlas datasets (TCGA), suggesting that E2F1 and PRMT5 regulate the process of cell migration and invasion." (PMID 37795443, 2023). "We obtained 74 dysregulated SRGs between normal and cancer tissues, among which six genes (RPS6KA6, ABI3, PTTG1, E2F1, CBX7, and SPOP) were associated with the OS of CC patients." (PMID 37768206, 2023). "This is consistent with past studies that showed genes such as E2F1 regulate cancer cell proliferation, self-renewal, and drug resistance and act as stemness regulators in tumors." (PMID 37791907, 2023). "E2F1 consisted with CDKs, cyclins, CDK inhibitors and the RB family of proteins forming a cyclin-dependent kinase (CDK)—retinoblastoma (Rb)-E2F1 regulatory axis has been found in almost all cancers." (PMID 37277745, 2023). "CircASPM was found to interact with miR-130b-3p and abolish its inhibitory effect on the activity of E2F transcription factor 1 (E2F1), which is related to several cancers and poor overall survival." (PMID 37415736, 2023). "Both PRMT5 and E2F1 regulated the expression of lncRNA genes and therefore impacted on the repertoire of peptides presented to the immune system by cancer cells." (PMID 36841868, 2023). "For this reason, we evaluated the prognosis value of E2F1 for human cancers in this article based on published data." (PMID 37277745, 2023). "It is through this interplay that both PRMT5 and E2F1 are able to regulate antigen presentation by cancer cells." (PMID 36841868, 2023). "Repeatedly, E2F1 has been reported to be involved in several types of cancer and regulate the transcription of genes of the S phase in the cell cycle." (PMID 37876309, 2023). "This complex role of E2F1 provides insight into how cancer cells can prevent oxidative stress while being highly proliferative." (PMID 36778475, 2023). "The arginine residue of E2F1, a key molecule in cancer cell growth, is the target of methylation by PRMT5." (PMID 36765032, 2023). "E2F1 was the ninth transcriptional regulator whose activity most strongly correlated with total HMT expression in a pan-cancer analysis (Spearman’s rho = 0.464, 2.56%ile)." (PMID 37883365, 2023). "In this study, we evaluated the prognostic value of E2F1 in cancer patients according to published data." (PMID 37277745, 2023).
cancer (continued). "Protein arginine methyltransferase (PRMT) 5 is over-expressed in a variety of cancers and the master transcription regulator E2F1 is an important methylation target." (PMID 36841868, 2023). "In recent years, RB/E2F1 has been the main regulator of cancer cell metabolism in advanced diseases." (PMID 36936419, 2023). "Due to its role in promoting proliferation, E2F-1 is exploited by cancers and it is overexpressed in many cancers, serving as an oncogene." (PMID 36766831, 2023). "This suggests that the effects of CDK inhibitors are mediated, at least in part, by increasing deregulated E2F1 activity, supporting the proposed treatment strategy of enhancing deregulated E2F activity in cancer cells, specifically inducing apoptosis." (PMID 36833320, 2023). "It is reported that the ARF promoter exhibits more cancer-cell specific activity than the previously utilized E2F1 promoter." (PMID 36833320, 2023). "We have previously shown that NUSAP1 is positively regulated by E2F1 and promotes cancer invasion and metastasis." (PMID 37047232, 2023). "CEBPD upregulation via the p38/CREB pathway with HMDB as an activator was shown to activate PPPARG2 and chop GADD153 while attenuating E2F1, leading to the death of cancer cells." (PMID 37047552, 2023). "E2F1 has been widely reported to regulate cell cycle and cell death and has a significant role in multiple cancer types." (PMID 37538797, 2023). "Analyses of previously published E2F1 ChIP-Seq data sets revealed strong E2F1 protein occupancy at several putative E2F binding motifs at the ACSL4 promoter in various cancer cell lines." (PMID 37183818, 2023). "KLF5 promotes the expression of E2F1, cyclin D1, and Rad51 in pancreatic cancer and assists in the G1/S phase progression of cancer cells." (PMID 36761967, 2023). "Different lncRNAs have been shown to modulate both YAZ/TAZ and E2F1 expression and activities, holding the capacity to foster or restrain the cancer-promoting role of these transcription factors." (PMID 37980331, 2023). "The most common motifs found across cancer types included one known motif (E2F1, motif ID: M4536_1.02), two unmethylation motifs (UM_235.9_3.32_0.65_1_SGCWCGCGGCGGC and UM_326.6_2.71_0.59_6_CGCGCCCCGY)." (PMID 37782656, 2023). "In view of its rich functionality, E2F1 plays complicated roles in the initiation and development of malignant tumors." (PMID 35440106, 2022). "ATAD2 is directly associated with estrogen-bound ERα and ACTR, and thus elevates the expression of ERα-targeted cell cycle regulators, such as cyclin D1, Myc, and E2F1, which promote cancer cell proliferation." (PMID 36139505, 2022). "Mostly studied in the context of cell-cycle regulation, a cancer-related E2F1-miRNA network has been documented." (PMID 36231008, 2022). "To demonstrate the clinical significance of E2F1 expression in GC, we firstly compared the E2F1 expression between cancer patients and normal tissues in TCGA database." (PMID 35440106, 2022). "In our work, we showed that genetic and chemical E2F inhibition reversed the resistance of PCa cells to 5-FU, in line with the findings of a recent study in various cancer cell lines using a small molecule that inhibits E2F1." (PMID 36230876, 2022). "More importantly, previous study has proven that E2F1/E2F3/Caspase-3 axis is an effective mechanism in cancer suppression which not only can advance apoptosis level in cancer cell but also inhibit stemness, invasion, migration, etc.." (PMID 36175803, 2022). "In line with this, it was recently shown that coactivators overexpressed in highly aggressive cancer stem cells (CSC phenotype) can direct E2F1 to enhance the transcription of metastasis-related genes." (PMID 36678712, 2022).
cancer (continued). "To study the genomic binding landscapes of p65 and E2F1 and their overlap in HeLa cancer cells, we re-analysed publicly available ChIP-seq data for p65 following TNFα stimulation, and E2F1 prior to TNFα stimulation." (PMID 36291831, 2022). "ZFP36-encoded protein, tristetraprolin (TTP), an RNA binding protein, plays an important role in cancer cell proliferation through destabilizing Cyclin D1 and E2F1 mRNA." (PMID 34983615, 2022). "To note, E2F1 (E2F transcription factor 1) is responsible for the maintenance of cancer cells stemness and E2F1 stabilization is controlled by phosphorylation at Ser364 via PP2A." (PMID 36345878, 2022). "We identified 1948 peaks for E2F1 and 8282 peaks for p65 in HeLa cancer cells, prior and upon TNFα stimulation, respectively." (PMID 36291831, 2022). "This study analyzed The Cancer Genome Atlas (TCGA) to screen potential candidate genes and the regulation network of KAT2A and E2F1 complex in pan-cancer." (PMID 36292703, 2022). "The majority of previous studies demonstrated that deregulated E2F1 facilitates premalignant or transformed cells to acquire multiple hallmarks of cancer, such as limitless replicative potential, metabolic reprogramming, metastasis, and ADT resistance." (PMID 36034466, 2022). "This difference can be explained, at least in part by the differential effects of JQ1 on the expression of E2F1 in these two cancer types." (PMID 36274096, 2022). "E2F1, a transcription factor highly expressed in cancer cells, has been widely reported to regulate the cell cycle in multiple biological processes, including mitotic spindle organization." (PMID 36221072, 2022). "From the GEPIA online analysis, we found that compared with the expression level distributed in a normal person, KAT2A was slightly higher in cancer patients, and E2F1 was obviously higher expressed in cancer patients." (PMID 36292703, 2022). "NRF1 is involved in cancer growth by regulating E2F1 transcriptionand also a valuable prognostic biomarker for LIHC." (PMID 35448958, 2022). "In the E2F family, E2F1 is the most extensively investigated member across different types of cancer." (PMID 35069909, 2022). "One novel potential regulatory mechanism of p63 involves E2F family members, notably E2F1 and E2F7, which regulate cell cycle gene expression in HPV infection and HPV-associated cancers." (PMID 35712470, 2022). "And it has been previously reported that IRF1 and E2F1 can regulate the proliferation and metastasis of various cancer cells by affecting their downstream genes 33-37." (PMID 35154468, 2022). "Both the expression levels of KAT2A and E2F1 were significantly up-regulated in the same 16 cancers, and E2F1 was also higher expressed in CESC, GBM, KICH, and UCEC cancers." (PMID 36292703, 2022). "Mechanistically, transcription factor E2F1 enhanced CKS2 expression through binding to its promoter and CKS2 regulated the cancer-associated PI3K–AKT pathway." (PMID 36096885, 2022). "For example, the lncRNA PLANE (Pan-cancer lncRNA activating NCOR2 responsive to E2F1) is generally upregulated in multiple cancer types via genomic amplification and E2F1-mediated transcriptional activation." (PMID 35427215, 2022). "Previous identified mRNA targets of ZFP36L1 include mRNAs that drive proliferation in other cancers including Cyclin D, E2F1, and NOTCH29,34." (PMID 36008402, 2022). "In fact, a complex co-regulatory network of E2F1 and microRNAs was described and termed the “E2F1-microRNA-cancer progression network”." (PMID 36231008, 2022). "Loose of the cell cycle regulation is central to this oncogenic proliferation, and dysregulation in markers (such as E2F1, PLK1, CCNE1, and CCND1) associated with cell cycle mechanism is one of the most prominent molecular aberrations in all cancers." (PMID 35419294, 2022). "JQ1 has been proven to be a first-in-class BETi, which can downregulate the transcription of multiple genes through targeting BRD4, such as MYC, IL7R, and E2F1 in different cancer cells." (PMID 36499487, 2022).